IL6 (interleukin 6)
Diseases named in the same sentence as IL6 in open-access papers (continued):
Sharing a sentence is not in itself a finding about the gene and the disease.
tumor (continued). "In line with the alterations of tumor microenvironment contributing to PCSLC expansion under ADT, a large set of evidence reveals a critical role of the IL-6/JAK/STAT3 pathway in PCSLC enrichment under ADT." (PMID 26593949, 2015). "Results showed that, in general, gene expression of tumor stroma was positively correlated with all signatures of activated fibroblasts (CAF, IL6 or TGFβ)." (PMID 26375444, 2015). "We show by immunofluorescent labelling that monolayers display phenotypic similarities with corresponding sphere cultures and primary tumours, and secrete clinically relevant inflammatory factors, including PGE2, VEGF, IL-6, IL-8 and IL-15." (PMID 26183281, 2015). "The mRNA expression of IL-6, a multi-functional cytokine required for MDSC generation and tumor progression, was predominantly increased in S100A9-expressing human tumors and mouse stroma." (PMID 26315114, 2015). "To better understand the relationship between tumour microenvironment parameters and cell invasion, we studied the effects of HGF, EGF, IGF, netrin, PDGF-B, TNF-α, bFGF, IL-6, NGF, TGF-β and PlGF-1 in the 3D environment." (PMID 26486848, 2015). "Expression levels of multiple genes encoding for cytokines or cytokine receptors over-expressed in tumor cells or ascites fluid, such as CXCL1, CXCL2, CXCL3, IL8, IL6, IL6R, and CXCR4 were reduced in OV3/COX1KD cells." (PMID 25972361, 2015). "Cytokines, such as TNF-α, IL-1α, IL-1β, IL-6, and TGF-β, are produced by tumor cells and tumor-infiltrating lymphocytes and can greatly influence cellular radiosensitivity and the onset of tissue complications." (PMID 26569225, 2015). "In particular, after TARGIT treatment, they observed that various proteins including IL-6, MCP-1 and IL-8, and STAT3-drived pathways involved in controlling tumour cell growth and motility, were deregulated." (PMID 25705130, 2015). "We have shown that endothelial cells secrete IL-6, CXCL8, and EGF that induce phosphorylation of STAT3, AKT, and ERK in tumor cells, and that these phosphorylation events enhance tumor cell survival and migration." (PMID 26287605, 2015). "For tumor growth studies, kidney RF thermal ablation alone, sham procedure, RFA/MNP anti-IL6 siRNA (20g of siRNA, IP delivery), and MNP anti-IL6 siRNA alone were compared (n = 6–7 animals/arm)." (PMID 26154425, 2015). "Repeated DEN-induced murine tumors share similar pathogenesis, where pro-inflammatory cytokines, such as interleukin-6 (IL-6) and tumor necrosis factor-α (TNF-α), promote tumor development." (PMID 26293671, 2015). "The IL-6/JAK/STAT3 pathway is appealing, as it links tumor-derived signaling and tumor microenvironment-initiated signaling." (PMID 26593949, 2015). "Recently, Loxoribin, a TLR7 agonist, has been shown to be able to shrink the tumor through augmenting the proliferation of CD4+ T cells and lowering the frequency of Tregs, which is mediated by elevated IL-6 level secreted by DCs." (PMID 26683520, 2015). "In the same manner, MCs can participate in tumor rejection, producing and releasing TNF-α and molecules such as interleukin 1 (IL-1), IL-4, and IL-6 that kill tumor cells." (PMID 25648323, 2015). "Peritumoral IL-6, IL-6R, gp130, CD68, and HIF-1α expression, as well as MVD, gradually increased during tumor growth." (PMID 26525581, 2015). "Our study found that daily oral intake of celecoxib or mushroom beta-glucan from Antrodia camphorata can decrease the gene expression of IL-6, IL-10, COX-2, and TGF-β and further decreases the proportion of M2 macrophages in tumor-bearing mice." (PMID 26167490, 2015). "A novel discovery was the role of tumor cell NF-κB on post-treatment immune signaling by macrophages, which led to a substantially higher release of TNF-α and IL-6 by macrophages." (PMID 26307977, 2015). "Cytokines such as, IL-6, TNF-α and IL-1β have been shown to be able to increase tumor cell pro-coagulant activity, enhancing clotting activation in cancer patients." (PMID 26192925, 2015).
tumor (continued). "The α-SMA together with IL-6 and transforming growth factor-β (TGF-β) are involved in (myofibroblast differentiation by up-regulation of miR-21 by interaction with PDCD4 in the tumor-stroma." (PMID 26010154, 2015). "Corroboratively, IL-6 production and secretion was highly stimulated in macrophages by PDT-treated tumor cell supernatants in a tumor cell death-dependent manner (this study)." (PMID 26307977, 2015). "Taken altogether, IL-6 seems to be beneficial for PDT outcome by deterring proliferation and stimulating anti-tumor immunity." (PMID 26307977, 2015). "Recently, many tumor markers such as SCCA, CEA, CA19-9, MMP-9, IL-6, CYFRA 21–1, DKK-1, M-CSF, MiR-18a, MiR-1246 and many other genes were evaluated for ESCC diagnosis." (PMID 25608466, 2015). "In our IHC data we found approximately 65 % of patient samples had positive IL-6 staining; however, when we examined IL-6 expression in our DCIS tumor cell lines, we found the expression to be near the lower threshold of our assay." (PMID 26268945, 2015). "We have previously reported attenuated levels of MCP1 and VEGF by Dox in PLF of MM tumor bearing SCID mice, however, IL-6 and IL-8 levels were significantly increased." (PMID 26689911, 2015). "Daily oral intake of mushroom beta-glucan in tumor-bearing mice increases the amounts of IL-12 and IFN-γ gene expression and lowers the gene expression of IL-6, IL-10, COX-2, and TGF-β in tumor tissues of tumor-bearing mice." (PMID 26167490, 2015). "Proinflammatory cytokines such as interleukin-6 (IL-6) and tumour necrosis factor alpha (TNF-α) have been suggested to play a certain role in variety of tumours." (PMID 25858079, 2015). "Existing data suggest that some cytokines, such as IL-6, IL-10 and VEGF, play an important role in KSHV-related cancer pathogenesis, including the promotion of tumor cell growth, angiogenesis, and the suppression of T cell activation." (PMID 24587336, 2014). "Our findings further build on these models by suggesting a role for ezrin in the regulation of IL-6 expression and Stat3 activation leading to the upregulation of VEGF-A/-C and tumour angio/lymphangiogenesis." (PMID 25231728, 2014). "Both HNSCC derived cell lines and invasive HNSCC tumor cells produce proinflammatory cytokines including IL-1β, TNF-α, and IL-6." (PMID 24465623, 2014). "Significant (P < 0.01) increases of the serum IL-6 levels, and decreases of IFN-γ levels were observed in tumor-bearing control mice as compared with intact control mice, respectively." (PMID 25477992, 2014). "These cytokines, such as tumor necrosis factor-α (TNF-α), interleukin-6 (IL-6), IL-8, IL-10, and macrophage inflammatory protein 1 (MIP-1), have been shown to stimulate angiogenesis and promote IR, as well as being pivotal to tumor development." (PMID 25069390, 2014). "IL-6 promotes CSC self-renewal, the recruitment of MSCs and immune cells, and the preservation of an inflammatory state that favors tumor growth." (PMID 25136593, 2014). "Levels of IGF-I, CXCL1, IL-6, and CCL2 were higher in BALF from tumor-bearing mice than naïve mice 32 weeks after urethane treatment, but VEGF levels were unchanged." (PMID 25505466, 2014). "DCs differentiated in the presence of adenosine express higher levels of VEGF, IL-6, IL-8, IL-10, COX2, TGFβ, and indoleamine 2,3-dioxygenase (IDO), thus sustaining tumor angiogenesis." (PMID 25072019, 2014). "In the present study, the secretion of IL-6, RANTES and GCSF was increased in the MUC2-knockdown tumor cells in comparison to the SR tumor cells." (PMID 25322805, 2014). "High levels of pro-inflammatory factors, such as GM-CSF, IL-1β, IL-6, and S-100 within the TUMIC induce recruitment and expansion of MDSCs, and enhance their pro-tumor activity." (PMID 25072019, 2014).
tumor (continued). "Additional repressed genes were ANGPTL2, TGM2, IL-6, CSF1R, TNFSF12 as well as a key regulatory MAP kinase ERK1/2 (MAPK3), all known to stimulate chronic inflammatory signaling in the tumor microenvironment and to promote cancer metastasis." (PMID 24498382, 2014). "IL-6 can reactivate latent HCMV virus in CD14+ monocytes and dendritic cells, and it is a pro-inflammatory cytokine commonly found in the tumor environment." (PMID 25549333, 2014). "Tumor neovascularization or angiogenesis is closely related with proangiogenic factors such as VEGF, IL-8, IL-6, TGF and TNF released by tumor cells and immune cells." (PMID 24555849, 2014). "We performed a protein array on tumor explant supernatants and found a significant decrease of monocyte chemotactic protein (1 MCP1) (CCL2), IL6, and tissue inhibitor of metalloproteinase (1 TIMP1) expression in cells expressing DNIIR." (PMID 25280532, 2014). "In this study, we examined the intracellular signaling pathway involved in IL-6-induced ICAM-1 expression and tumor migration in human OSCC." (PMID 24398980, 2014). "Tumor tissue was analyzed for relative mRNA expression of a panel of different cytokines (IL1 β, IL2, IL6, IL18, TNF-α and IFN-γ)." (PMID 24676901, 2014). "IL-6 increases ICAM-1 expression through the IL-6R, Syk, JNK, and AP-1 signaling pathways and induces tumor migration." (PMID 24398980, 2014). "Such epithelial permeability results in the stimulation of macrophages and granulocytes in mucosal tissue followed by cytokine production such as IL-1β, IL-6 and MIP-2 that are required for epithelial proliferation and tumor development." (PMID 24520376, 2014). "An IL6-neutralizing antibody inhibited VEGF secretion and tumor proliferation in the co-culture system." (PMID 24885802, 2014). "For example, MSC-secreted IL-6 has been shown to maintain MSC stemness, promote adenocarcinoma tumour growth, delay neutrophil apoptosis and inhibit progenitor cell differentiation into dendritic cells by impairing their antigen-presenting function." (PMID 25250510, 2014). "The tumor regression by DOX and combination was also mediated through increased expression of IL-6 levels." (PMID 25177685, 2014). "We then assessed DCOVA/IL-6-stimulated cytotoxic T-lymphocyte (CTL) responses and antitumor immunity in OVA-specific animal tumor model." (PMID 24690994, 2014). "This was supported by the inverse correlation between E-cadherin and IL-6 expression, positive correlation between IL-6 and vimentin mRNA expression and between STAT3 phosphorylation and IL-6 expression in tumor tissues." (PMID 24789104, 2014). "Cell senescence is associated with a distinct cytokine and cytokine receptor expression signature and FUS-DDIT3 is known to induce IL6 and IL8 expression in the tumor cells." (PMID 25093008, 2014). "Our data indicate that kynurenine, produced by IDO in tumor cells, activates the AHR, thereby inducing IL-6." (PMID 24657910, 2014). "Recent studies implicate myeloid derived suppressor cells (MDSC) in the induction of CD8+ T cell tolerance in tumor-bearing hosts and that appear to be recruited by tumor-derived soluble factors such as TGF-ß1, IL-10, VEGF, GM-CSF, IL-6 and prostaglandin E2." (PMID 24457057, 2014). "We observed that blockade of endothelial cell-derived IL-6 inhibited STAT3 phosphorylation in cancer cells and expression of CXCL8 (IL-8), a potent pro-angiogenic factor that is strongly correlated with tumor microvessel density." (PMID 24533454, 2014). "This tumor produced interleukin (IL)-8, granulocyte colony-stimulating factor and IL-6, which in turn recruited inflammatory cells, such as CD8 positive lymphocytes, around the tumor, resulting in a rapidly growing tumor shadow." (PMID 25123545, 2014). "Both exogenous IL-6 and TGF-β induced EGFR inhibitor resistance and endogenous TGF-β was produced from EGFR inhibitor resistant tumor cells." (PMID 25240937, 2014).
tumor (continued). "Gemcitabine 160 mg/kg treated mice showed significant (P < 0.05) aggravated the serum IL-6 and IFN-γ level changes, induced by H520 tumor-bearing in this study." (PMID 25477992, 2014). "For instance, IL-17 up-regulates the secretion of pro-angiogenic and pro-tumor factors (e.g., VEGF, IL-6, and IL-8) by stromal cells and fibroblasts, thus promoting angiogenesis and sustained chronic inflammation." (PMID 25538706, 2014). "In PCa, STAT3 activation associated with decreased AR expression is mediated through increased production of IL-6 and treating mice with soluble IL-6 receptor fusion protein significantly reduces CSC number and xenograft tumor growth." (PMID 24722453, 2014). "EGFR inhibition induces tumor cells to the mesenchymal phenotype, which cell type show resistant to EGFR inhibitor, via cytokines such as IL-6 and TGF-β." (PMID 25240937, 2014). "STAT3 has been proposed as a therapeutic target for tumor cells as it is a downstream mediator of EGFR and IL6, both of which have been shown to be important in carcinogenesis and angiogenesis." (PMID 24404126, 2014). "In line with this, macrophage-specific SOCS3 knockout animals are resistant to tumor transplantation due to reduced secretion of tumor-promoting TNF-α and IL-6, together with elevated MCP2/CCL8 that is anti-tumorigenic." (PMID 25120543, 2014). "As a consequence, TLR8 is activated and the immune cells release interleukin-6 (IL-6) and tumor necrosis factor alpha (TNF-alpha), which increase tumor growth and metastatic potential." (PMID 25356314, 2014). "Senescent cells also secrete factors such as WNT16B, interleukin-6 (IL-6), and tissue inhibitor of metalloproteinases-1 (TIMP-1) that can protect neighboring tumor cells from being killed." (PMID 24981831, 2014). "HNSCC cells trigger increased IL-6 production from CD34+ progenitor cells, for example, promoting angiogenesis in the tumor microenvironment." (PMID 24698959, 2014). "The resulting stromal modifications (increased vessel stability and matrix degradation) are compatible with tumor expansion, stimulated simultaneously by CAFs release of tumor-supportive growth factors, including HGF, EGF, IL-6 and SDF1." (PMID 25303976, 2014). "Secondly, circulating neutrophils contributes to tumor growth and progression by producing cytokines, such as tumor necrosis factor (TNF), IL-1, IL-6, and angiogenic factor vascular endothelial growth factor (VEGF)." (PMID 25401500, 2014). "In order to elucidate this, the JAK2/STAT3 signaling pathway was downregulated in the present study, as IL-6 and STAT3 work together in the tumor microenvironment to promote several cancer hallmarks, for example increased proliferation, survival and invasion." (PMID 24527098, 2014). "Amongst the released factors is IL-6, which has been reported to promote GSC survival and tumour growth." (PMID 24879067, 2014). "The potent anti-tumor activity of YM155, at least in MM, therefore seems to be mediated by the activation of the unfolded protein response and simultaneous abrogation of IL-6/STAT3 signaling." (PMID 25296978, 2014). "Here we show that GSH levels in metastatic cells, which are regulated by the IL-6/GSH interorgan cycling activity (where the liver provides GSH to metastases), directly influence the effect of corticosterone on tumor cell viability." (PMID 23517603, 2013). "The liberation of multiple proinflammatory cytokines, including IL-1, IL-6, and TNF-α from the tumor microenvironment results in the induction of CRP synthesis from the liver." (PMID 24130817, 2013). "IL-6, EGFR and HSPA8 act as survival factors for neoplasm and increased circulating levels of these proteins have been observed in various types of cancer patients." (PMID 23414419, 2013). "mRNA expression of CD44 was also measured for all conditions (IL-6, TNF-α, tumor spheroid, and plasma) via real time quantitative PCR (qPCR)." (PMID 23372803, 2013).
tumor (continued). "High expression of IL-6 and TNFα exhibited a close correlation with high expression of VEGF in the tumor cells (r = 0.714, p < 0.0001 and r =0.702, p < 0.0001 respectively)." (PMID 23688241, 2013). "In gastric cancer, activated monocytes promote the development of Tc17 cells via IL-6, IL-1β, and IL-23, resulting in the production of the chemokine CXCL12 by tumor cells, which promotes MDSCs-mediated immunosuppression." (PMID 24382972, 2013). "As IL-1α, IL-2, IL-6, TNF-α and IFN-γ are the major inflammatory cytokines secreted by immune cells activated by PHA, they are also located in the tumor microenvironment." (PMID 23761816, 2013). "Interleukin-6 (IL-6) is one NF-kB-dependent cytokine, which induces the oncogenic transcription factor STAT3 in order to promote proliferation and survival of tumor-initiating intestinal epithelial cells, thus contributing to CAC tumorigenesis in mice." (PMID 25437036, 2013). "The effect was potentiated when mice were inoculated with cancer cells, previously knocked down of IL-6, thus confirming the role of IL-6 as a strong chemotactic factor that recruits TAM to the tumor lesion." (PMID 23533771, 2013). "In this model, IL-1α-induced IL-6 activates STAT3 and promotes liver regeneration and tumor outgrowth." (PMID 23847618, 2013). "Although some cytokines can promote tumour proliferation in certain models, the biological functions of the SASP are complex, as some components such as IL-6 and IL-8 actively participate in the maintenance of cellular senescence." (PMID 23180582, 2013). "Increased IL-6-induced activation of STAT3 was observed in neoplastic gastric tissue, which positively correlated with tumor progression." (PMID 24116074, 2013). "Deletion of IL-6 or its cognate receptor gp130 in AOM/DSS model resulted in reduced tumor size and tumor number, whereas further potentiation of STAT3 activity by introducing hyper-active gp130 led to increased tumor diameter and tumor count." (PMID 23940556, 2013). "The circulating angiogenic factors such as vascular endothelial growth factor (VEGF), interleukin 6 (IL-6), interleukin 8 (IL-8), and platelet-derived growth factor (PDGF) were positively correlated with tumor angiogenesis." (PMID 23985826, 2013). "IL-6/STAT3 signaling has been identified to link with the transition of HR and aggressive tumor behavior." (PMID 23806095, 2013). "The combination of IL-6 and its inducers TNF-α and IL-1β promotes tumor growth and survival in cancer patients through maintenance of chronic inflammation and induction of a tumor-supporting microenvironment." (PMID 23616009, 2013). "In this model, early increases in IL-6, IL-8 and VEGF in lavage fluids are produced by both epithelioid and sarcomatoid MM after their injection into mice that precede tumor development." (PMID 23937860, 2013). "Immunostaining signal of IL-6, TNFα and VEGF was localized in the cytoplasm of tumor cells and CD34 was localized in endothelial cells of newly formed vessels." (PMID 23688241, 2013). "In fact, either genetic deletion of NF-κB or IL-6, or the inhibition of inflammatory cytokines, such as TNF-α, determined a significant reduction in HCC tumor load." (PMID 23533994, 2013). "TAM-derived IL-6 seems also to favor the epithelial-mesenchymal transition of HCC, which has an important role in tumor progression." (PMID 23533994, 2013). "IL-6 signaling has been shown to be TGF-beta dependent, where suppression of TGF-beta led to decreased STAT activation and the prevention of in vivo tumor progression." (PMID 24098947, 2013). "The inflammatory markers IL6 and IL8 as well as the potential HPV receptor ITGA6 were significantly elevated while IL12A was downregulated in the tumour tissues." (PMID 23570247, 2013). "Specifically, we show that EVs are potent stimulators of MMP-9, IL-6, TGF-β1 and induce the secretion of extracellular EMMPRIN, which all play a role in driving immune evasion, invasion and inflammation in the tumor microenvironment." (PMID 23936495, 2013).